OR1L3 (olfactory receptor family 1 subfamily L member 3)
Description:
Odorant receptor.
Synonyms: OR9-D; OR9-28
Tractability: Antibody: UniProt places it where antibodies can reach, with medium confidence; UniProt predicts a signal peptide or a membrane-spanning region; its Gene Ontology location is reachable by antibodies, with medium confidence.
Gene: Protein-coding gene on chromosome 9 (122,675,130 to 122,676,104, forward strand). Ensembl gene ENSG00000171481.
Subcellular location: Cell membrane
Pathways (Reactome):
Sensory Perception: Expression and translocation of olfactory receptors
Gene Ontology:
Molecular function: protein binding; olfactory receptor activity; G protein-coupled receptor activity; signaling receptor activity
Biological process: signal transduction; detection of chemical stimulus involved in sensory perception of smell; G protein-coupled receptor signaling pathway; sensory perception of chemical stimulus
Cellular component: plasma membrane; membrane
Genetic constraint (gnomAD): Loss-of-function variants: 0 observed, 0.22 expected, observed/expected ratio (o/e) 0, 90% interval 0 to 1.88. That is too few expected variants to judge how well the gene tolerates losing a copy. Missense variants: 374 observed, 405.26 expected, observed/expected ratio (o/e) 0.92, 90% interval 0.85 to 1. Synonymous variants: 137 observed, 153.65 expected, observed/expected ratio (o/e) 0.89, 90% interval 0.77 to 1.03.
Homologues: Orthologues: chimpanzee OR1L3 (86% identical), rabbit OR1L3 (78% identical). Paralogues in human: OR1L1 (75% identical), OR1L8 (65% identical), OR1L6 (63% identical), OR1L4 (63% identical), OR1M1 (50% identical), OR7C1 (50% identical), OR1C1 (49% identical), OR1N1 (49% identical), OR1N2 (49% identical), OR1J2 (49% identical), OR7A5 (49% identical), OR1E1 (48% identical), and 116 more.
Diseases named in the same sentence as OR1L3 in open-access papers:
OR1L3 is named in the same sentence as 3 diseases in open-access papers, as found by Europe PMC text mining. Sharing a sentence is not in itself a finding about the gene and the disease. The quoted sentences say what the papers report.
cholangiocarcinoma (1 paper, 2021). A carcinoma that arises from the intrahepatic biliary tree (intrahepatic cholangiocarcinoma) or from the junction, or adjacent to the junction, of the right and left hepatic ducts (hilar cholangiocarcinoma). "The top-ranked somatic eQTL genes with missense mutations include USP29 in cholangiocarcinoma (CHOL) and AMELX, CNTN5, and OR1L3 in lymphoid neoplasm diffuse large B-cell lymphoma (DLBC)." (PMID 33691015, 2021).
OR1L3 also shares sentences with these, for which no sentence is quoted: diffuse large B-cell lymphoma (1 paper); lymphoid neoplasm (1).